ATM (ATM serine/threonine kinase)
Diseases named in the same sentence as ATM in open-access papers (continued):
Sharing a sentence is not in itself a finding about the gene and the disease.
breast cancer (continued). "It has long been known that female carriers of an ATM mutation are at increased risk of breast cancer." (PMID 39543654, 2024). "In 2017, the National Comprehensive Cancer Network (NCCN) made recommendations regarding adjuvant RT of breast cancer for women carrying a monoallelic ATM pathogenic variant." (PMID 38611095, 2024). "On the other hand, radiotherapy has always been a hallmark of breast cancer treatment; but there has been considerable discussion regarding its safety in patients with ATM mutations, given their known increased radiosensitivity." (PMID 39543654, 2024). "On the other hand, Germline PVs in ATM are associated with a moderate increase in the risk of breast cancer in women of 20%–40% in life, pancreas of 5%–10%, ovarian of up to 3% and unspecified prostate cancer risk." (PMID 39021548, 2024). "Overall, these results argue against recommending contralateral prophylactic mastectomy for reducing contralateral breast cancer in ATM pathogenic variant carriers." (PMID 39543654, 2024). "According to previous reports, the ATM gene is associated with an increased risk of various cancers, such as breast cancer, lung cancer, pancreatic cancer, and melanoma." (PMID 39009979, 2024). "Regardless of these discrepancies, caspase-2 has been assigned tumor suppressor potential in animal models of MMTV/c-neu–driven breast cancer, ataxia-telangiectasia mutated (ATM) loss, and MYC-driven lymphomagenesis." (PMID 39475598, 2024). "Several case-control studies have been done to estimate the odd ratio for developing breast cancer for ATM mutation carriers." (PMID 39543654, 2024). "ATM mutations cause ataxia-telangiectasia (AT) and have been associated with a risk of breast cancer." (PMID 38350919, 2024). "In a second large study (CARRIERS study) the prevalence of ATM mutations came from sequencing large number of unselected breast cancer patients and controls." (PMID 39543654, 2024). "In Sweden, only truncating ATM variants are considered actionable, but the missense variant detected in our study is a Finnish founder, with an increased risk of breast cancer." (PMID 39594770, 2024). "In the current paper, we review the risks of breast and ovarian cancer (penetrance) and discuss the management of breast cancers that occur in carriers of an ATM mutation." (PMID 39543654, 2024). "The interplay between radiation exposure and breast cancer risk is intricate for patients harboring ATM PVs." (PMID 38397209, 2024). "At present women with breast cancer diagnosed under age 65 are recommended to have genetic testing for ATM mutations as part of a comprehensive panel." (PMID 39543654, 2024). "It is important that large prospective studies be conducted looking at various treatment modalities in women with breast cancer and an ATM mutation in order to optimize outcomes." (PMID 39543654, 2024). "Despite this radiosensitivity, adjuvant radiation remains safe for most breast cancer patients who harbor ATM mutations." (PMID 39640102, 2024). "For this reason, it is important to know if radiotherapy as used for the treatment of breast cancer post-surgery is beneficial or poses hazards to women who carry an ATM mutation." (PMID 39543654, 2024). "In United States, a high prevalence of 6.6% was found in ATM, and many ATM mutations have been described and associated with a moderate risk of developing breast cancer." (PMID 39272924, 2024). "Among these variants, c.6115G>A (E2039K) in the ATM gene is of particular interest since it was identified in families with multiple cases of breast cancer (more than 6 cases)." (PMID 38313678, 2024). "One of them, i.e., ATM p.D1853N, has been previously reported; however, it is considered of least predictive value and has a weak association with developing breast cancer." (PMID 38784039, 2024).
breast cancer (continued). "The authors reported that women carrying missense variants of uncertain significance (VUS) in ATM had an elevated risk of CBC contralateral breast cancer, particularly among those who underwent RT (RR = 2.98, 95% CI = 1.31–6.80)." (PMID 39543654, 2024). "Previous studies have shown that heterozygous carriers of ATM gene mutations have a 2-5-fold increased risk of developing breast cancer." (PMID 38313678, 2024). "The probability of breast cancer diagnosis at age 70 in individuals with a pathogenic variant in ATM of CHEK2 and in the top 50% of the PRS distribution was 39.2%, whereas those in the bottom 50% of the PRS distribution had a risk of only 14.4%." (PMID 39669587, 2024). "Women with an ATM mutation have a lifetime risk of breast cancer of approximately 25%, the majority of which are ER-positive." (PMID 39543654, 2024). "A recent study by the Breast Cancer Consortium found an ATM mutation in 294 of 60,466 women with breast cancer (0.49%) and 150 or 53,461 controls (0.28%) (OR 2.10, 95% CI 1.71–2.57)." (PMID 39543654, 2024). "Future studies should also consider various chemotherapy regiments, in the neoadjuvant and adjuvant setting to see the relative effectiveness in preventing distant recurrence and mortality in women with breast cancer and an ATM mutation." (PMID 39543654, 2024). "Heterozygous loss-of-function (LoF) variants in ATM are associated with approximately 2-fold increased lifetime risks for breast cancer (MIM#114480) with a penetrance of 20-30%; and a 6.5-fold increased risk for pancreatic cancer 7-11." (PMID 38854136, 2024). "Studies have shown that elevated expression of ATM is associated with radioresistance in various tumors, including breast cancer, lung cancer, and gliomas, while ATM inhibitors can enhance the sensitivity of these tumor cells to radiotherapy." (PMID 38993643, 2024). "Other homologous recombination DNA damage repair (HR-DDR) genes associated with breast cancer risk accounted for 15.9% (13/82) of the carriers, including ATM (n = 2), BARD1 (n = 4), CHEK2 (n = 1), PALB2 (n = 2), RAD51C (n = 1), and RAD51D (n = 3)." (PMID 38893140, 2024). "FDA-approved therapies specific to breast cancer include Olaparib, which has demonstrated clinical efficacy for patients with ATM, BRCA1/2, and CHEK2 mutations, as well as alpelisib for patients with PIK3CA mutations." (PMID 38927753, 2024). "In the CARRIERS study an ATM mutation was found in 253 of 32,247 breast cancer patients (0.78%) and in 134 of 32,544 controls (0.41%)." (PMID 39543654, 2024). "The efficacy of PARPi in breast cancer (BC) patients with ATM pathogenic variants (PVs) is currently under examination within the metastatic setting." (PMID 38397209, 2024). "Germline mutations of homologous recombination genes such as ATM are involved in breast cancer susceptibility." (PMID 36769287, 2023). "The authors identified protein-truncating variants in BRCA1, BRCA2, CHEK2, PALB2 and ATM that were significantly associated with breast cancer risk." (PMID 37662839, 2023). "Studies have shown that germline mutations in ATM are associated with an increased risk of developing breast cancer, particularly in the context of familial breast cancer cases." (PMID 38327652, 2023). "The data presented here showed that the presence of familial breast cancer was more strongly associated with PV carrier status for ATM, BRCA1, BRCA2, CHEK2, and PALB2, in affected women (similar to previous studies)." (PMID 37084156, 2023). "Protein-truncating variants in BRCA2 and ATM were associated with a high risk of breast cancer, whereas PTVs in BRCA1 and PALB2 were associated with a high risk of estrogen receptor (ER)-negative disease." (PMID 37790698, 2023).
breast cancer (continued). "Conversely, we find that ATM mutations enrich for incidence of primary ER+/HER2− breast cancer that is preferentially PR−." (PMID 37390209, 2023). "Here we examined the impact of two traditional markers of hereditary cancer risk (age at breast cancer diagnosis and family cancer history) on the risk of carrying a PV in the most commonly mutated breast cancer-risk genes: ATM, BRCA1, BRCA2, CHEK2, and PALB2." (PMID 37084156, 2023). "Although ATM is typically most associated with a moderate increase in female breast cancer risk, we found tumor/germline variants in ATM distributed across virtually all tumor types studied." (PMID 36261688, 2023). "At the ATM locus, the presence of rs664677 and rs609429 in a homozygous state was linked to heightened breast cancer risk." (PMID 37761360, 2023). "Their research demonstrated a correlation between ATM variants and the susceptibility to breast cancer." (PMID 38201513, 2023). "We further provide population-specific evidence for the association of BRCA2 and ATM PTVs with overall breast cancer risk, and ER-negative breast cancer for PALB2 PTVs." (PMID 37790698, 2023). "Among participants with a family history of breast cancer, PTVs in ATM, BRCA2, BRCA1, PALB2 and RAD50 were associated with an increased risk of breast cancer." (PMID 37790698, 2023). "Recent studies have revealed a significant association between ATM variants and the risk of multiple types of cancers, particularly breast cancer." (PMID 37951143, 2023). "ATM mutations were found to be associated with an increased risk of breast cancer and ATM loss of function was reported in familial breast cancer patients." (PMID 37202799, 2023). "On the other hand, low ATM expression is found to be correlated with increased tumor-infiltrating CD8+ T cells in breast cancer and fumarate hydratase-deficient renal cell carcinoma." (PMID 37174688, 2023). "The second proband with bi-lateral breast cancer had a homozygous pathogenic variant (c.6067G>A) in the ATM gene identified by WES analysis." (PMID 38327652, 2023). "Heterozygous pathogenic variant in ATM is associated with a 13-33% cumulative lifetime risk for breast cancer." (PMID 37781190, 2023). "Carriers of pathogenic ATM variants have a 2 to 4-fold increased risk of developing breast cancer, especially early-onset cancer and bilateral breast cancer." (PMID 37951143, 2023). "The deleterious variants in ATM have been demonstrated that it is a moderate penetrance gene correlated with increased susceptibility to breast cancer." (PMID 37323311, 2023). "Several other studies have reported similar findings, with ATM mutations identified in women <45 years of age and a higher frequency in cases with a positive family history of breast cancer." (PMID 36980802, 2023). "Loss of 21p11.2-p11.1 has been observed in breast cancer patients with pathogenic ataxia telangiectasia mutated (ATM) gene variants." (PMID 37048158, 2023). "We generated two induced pluripotent stem cell (iPSC) lines from peripheral blood mononuclear cells (PBMCs) of breast cancer patients carrying germline ATM mutations, a gene associated with a 7% prevalence in breast cancer." (PMID 37951143, 2023). "Mutations in the ATM gene can lead to ataxia telangiectasia, breast cancer, and increased susceptibility to cancer development." (PMID 38327652, 2023). "ATM (9, 6.3%), the third most common variant, was found in pancreatic (2.1%) and breast cancer (3.5%)." (PMID 38201513, 2023). "Heterozygosity for ATM gene variants increases the risk of development of breast cancer by 2-3-fold compared to the general population." (PMID 37277882, 2023). "Together, these results indicate that the synergistic cytotoxicity of combined EZH2/ATM inhibition in BRCA1-deficient mouse mammary tumor cells is mediated by apoptosis." (PMID 35715861, 2022). "The estimated breast cancer hazard ratio for carriers of pathogenic ATM variants in the ABCFR was 1.32 (95% confidence interval 0.45–3.87; P = 0.6)." (PMID 35365198, 2022).
breast cancer (continued). "Patient BRB14 (Zulu-speaking patient), diagnosed with breast cancer at age 47 years and 8 months, was a carrier of the novel ATM likely pathogenic variant, c.162T > A." (PMID 35039564, 2022). "An analysis of 27 families with ATM PVs showed an association between the c.7271T>G variant and increased risk for breast cancer (hazard ratio (HR), 8.0; 95% CI, 2.3–27.4; p < 0.001)." (PMID 35008949, 2022). "There are lines of evidence indicating that the carriers of pathogenic ATM mutation, accounting for 1–2% in human populations, exhibit a several-fold increased risk of breast cancer." (PMID 35457081, 2022). "Multigene panel tests for breast cancer predisposition routinely include ATM as it is now a well-established breast cancer predisposition gene." (PMID 35365198, 2022). "Studies of A-T families showed that heterozygous ATM pathogenic variant (PV) carriers are at increased risk of breast cancer." (PMID 36555667, 2022). "estimated an OR of 1.8 (95% CI 1.46–2.27, p < 0.001) and, by combining this OR with the SEER breast cancer incidence rates for the population, derived an estimate of lifetime absolute risk of breast cancer greater than 20% for ATM pathogenic variant carriers." (PMID 35365198, 2022). "Targeting ATM signaling is currently evaluated in HR-deficient breast cancer in several phase I and II trials, corroborating the clinical significance of our approach." (PMID 35715861, 2022). "Beside CVDs, ATM variants have been associated with conveying an increased risk of developing some cancers, including chronic lymphocytic leukemia, breast cancer, pancreatic cancer and mantle cell lymphoma." (PMID 35872888, 2022). "Targeted enrichment sequencing of the panel of 32 known or suspected breast cancer susceptibility genes confirmed the associations of known breast cancer susceptibility genes ATM, CHEK2, and PALB2." (PMID 35884425, 2022). "The predicted proportion of breast cancer cases possessing pathogenic germline missense variants in these genes is approximately 0.6%, 0.3%, 0.2%, and 1.3% for ATM, BRCA1, BRCA2, and CHEK2, respectively." (PMID 35585550, 2022). "The estimated cumulative risk of breast cancer to age 80 years for heterozygous ATM pathogenic variant carriers was estimated to be 13% (95% CI 4.6–30)." (PMID 35365198, 2022). "The current validation study successfully detected confirmed breast cancer susceptibility genes such as ATM, CHEK2, and PALB2." (PMID 35884425, 2022). "The induction of autophagy by oxidative stress is thought to contribute to the long-term survival of breast cancer cells by regulating DNA repair via ataxia telangiectasia mutated (ATM), DNA-PKcs, and poly (ADP-ribose) polymerase (PARP)-1." (PMID 35326612, 2022). "Mel_1, carrying the p.Ser1135_Lys1192del PV, showed loss of ATM and pATM expression in both breast cancer tissue and melanoma." (PMID 36555667, 2022). "Our study design shows that we had the power to detect genes with effect sizes similar to some confirmed breast cancer susceptibility genes, such as ATM and CHEK2." (PMID 35884425, 2022). "Because of an almost three times increased risk of developing breast cancer, heterozygous women harboring an ATM mutation should be offered an intensified surveillance program for breast cancer." (PMID 35454905, 2022). "ATM is a master regulatory kinase which is active in response to DNA damage, carriers of heterozygous variants are at risk of breast cancer and, potentially, pancreatic cancer." (PMID 36232851, 2022).
breast cancer (continued). "For the ATM gene, rs228591 was found to be associated with ATM expression in breast tumors (p-value = 0.000362) and rs227073 was located in breast cancer-associated enhancer targeting ATM gene." (PMID 35333900, 2022). "Patients with A-T and their female family members with heterozygous mutant ATM should start the screening for breast cancer earlier than the general population, and this age depends on the type of the mutation in the ATM gene." (PMID 35887984, 2022). "In particular, rare mutations in other breast cancer susceptibility genes, such as ATM and PALB2, are also likely to be associated with an increased risk of CBC." (PMID 36271417, 2022). "Overexpression of ATM indicates radiation resistance in breast cancer cells, whereas deficiency of ATM showed radiation sensitizer effects in multiple cancer types." (PMID 35875060, 2022). "Currently, the truncating variant R805X has been described only in breast cancer, however truncating mutations in ATM such as stop gain or frameshift were also found in familial PCa." (PMID 35347810, 2022). "The estimated breast cancer HR for carriers of pathogenic ATM variants in the ABCFR was 1.32 (95% CI 0.45–3.87; P = 0.6)." (PMID 35365198, 2022). "For ATM, as is the case for most breast cancer predisposition genes, truncating variants are, with a few exceptions, predicted to lead to loss of protein function and are classified as pathogenic." (PMID 35365198, 2022). "In a meta-analysis of three cohort studies that evaluated the relatives of A-T patients, the estimated relative risk of breast cancer was 2.8 (90% confidence interval (CI), 2.2–3.7; p < 0.0001) for ATM PV carriers." (PMID 35008949, 2022). "A similar sensitivity of olaparib in ATM deficient cells was also observed in two breast cancer cell lines." (PMID 36233063, 2022). "Heterozygous pathogenic variants in the ATM gene are associated with an increased risk of estrogen receptor positive breast cancer." (PMID 35806449, 2022). "Our data suggest that EZH2 inhibition can be combined with ATM inhibition to provoke toxic DSBs leading to apoptosis-mediated cell death in BRCA1-deficient breast cancer cells." (PMID 35715861, 2022). "Other analyses of patients receiving germline MGP genetic testing for cancer predisposition genes demonstrated that ATM PVs were associated with a moderate risk of breast cancer with an odds ratio (OR) of 2.03 or 2.78." (PMID 35008949, 2022). "These genes include “moderate penetrance” breast cancer susceptibility genes such as ATM and CHEK2, mutations in which are associated with a 2‐4‐fold increase in lifetime risk of female breast cancer." (PMID 36054727, 2022). "In a multicenter case–control study genotyping 10 rare variants in PALB2, CHEK2, and ATM, strong evidence of an association with breast cancer risk was observed for ATM c.7271T>G at an OR of 11.0 (95%CI, 1.42–85.7; p = 0.0012)." (PMID 35008949, 2022). "More recently, the largest WES study for overall breast cancer reported increased breast cancer risk associated with ATM, CHEK2, PALB2, and MSH6." (PMID 35884425, 2022). "In all but one case, the variants were still reported because of risk for later-onset cancers, such as breast cancer in ATM and PALB2 mutation carriers." (PMID 36182817, 2022). "Association between the ATM and breast cancer risk was analyzed by pooling odds ratio (ORs) and risk ratio (RR) with 95% confidence interval (CIs) using STATA metan module." (PMID 33402103, 2021). "Subgroup analysis based on continent shows that ATM variants have a greater impact on breast cancer incidence in the Asian population than in the European and American populations." (PMID 33402103, 2021).